NUPR1 (nuclear protein 1, transcriptional regulator)
Diseases named in the same sentence as NUPR1 in open-access papers (continued):
Sharing a sentence is not in itself a finding about the gene and the disease.
Parkinson disease (2 papers, 2023 to 2024). A progressive degenerative disorder of the central nervous system characterized by loss of dopamine producing neurons in the substantia nigra and the presence of Lewy bodies in the substantia nigra and locus coeruleus. "Using this pipeline for genes in Parkinson’s disease with oxidative stress revealed two unexploited genes: nuclear protein 1 (NUPR1) and ubiquitin-like with PHD and ring finger domains 2 (UHRF2)." (PMID 39154038, 2024). "We first tested the accuracy of two machine learning-built models and finally chose to use the random forest to obtain five Parkinson’s disease FRHGs (CISD1, SIRT2, NUPR1, ADAM23 and NEDD4L)." (PMID 38127902, 2023). "The top 5 genes were extracted as FRHGs in Parkinson’s disease (CISD1, SIRT2, NUPR1, ADAM23 and NEDD4L)." (PMID 38127902, 2023). "We obtained eight Parkinson’s disease ferroptosis-related genes (MAP3K11, SNX4, SIRT2, NUPR1, ACSL4, CISD1, ADAM23 and NEDD4L) by taking intersections of key genes of these two PD modules with ferroptosis-related genes." (PMID 38127902, 2023). "We combined WGCNA and random forest algorithm to obtain two new FRHGs (NUPR1 and ADAM23) in Parkinson’s disease, which are expected to be new PD biomarkers and drug action targets." (PMID 38127902, 2023). "Green module was obtained for five Parkinson’s disease FRGs (MAP3K11, SNX4, SIRT2, NUPR1, and ACSL4)." (PMID 38127902, 2023).
renal cell carcinoma (2 papers, 2021 to 2025). "Notably, enrichment analysis showed that overexpression of NUPR1 was associated with the cancer pathway, cancer cell stemness, mTOR pathway and renal cell carcinoma." (PMID 34030133, 2021). "Additionally, a bulk RNA‐seq dataset from a renal cell carcinoma mouse model treated with PD‐1 therapy supported our findings, showing higher NUPR1+ macrophage expression in immunotherapy‐resistant tumors." (PMID 40305758, 2025).
adenoma (1 paper, 2015). A neoplasm arising from the epithelium. "In this experiments, Nupr1+/+ developed a significant number of adenomas grade 1 and 2 (29.1 ± 11.3 and 6.5 ± 2.3 per slice) while Nupr1–/– mice developed fewer lesions (1.5 ± 1.0 and 0.1 ± 0.1 lesions)." (PMID 26617245, 2015).
atopic asthma (1 paper, 2023). An asthma that is characterized by symptoms that are triggered by an allergic reaction caused by inhaled allergens such as dust mite allergen, pet dander, pollen and mold. "Notably, MSL1, MOCS2, NUPR1, and SGF29 interact with proteins encoded by three genes that are associated with post bronchodilator FEV1, atopic asthma and AD." (PMID 36574990, 2023).
cardiomyopathy (1 paper, 2023). A disease of the heart muscle or myocardium proper. "Genes associated with ER stress (e.g., ATF4, NUPR1, DDIT3, TRIB3, CHAC1, SESN2, HERPUD1) were upregulated and genes related to cardiomyopathy and sarcomeric structure (e.g., MYH7, SYNPO2L, LDB3, ACTN2, MYLK3) were downregulated by afatinib, sorafenib, or high-dose ponatinib." (PMID 37069550, 2023).
cataract (1 paper, 2025). Partial or complete opacity of the crystalline lens of one or both eyes that decreases visual acuity and eventually results in blindness. "Our study explored the role of CHOP and Nupr1 in endoplasmic reticulum stress-induced apoptosis of lens epithelial cells to determine their specific mechanisms in cataract pathogenesis." (PMID 38771421, 2025). "Our study found that CHOP and Nupr1 are interacting proteins, and the addition of Nupr1 inhibitor ZZW-115 can reverse the promoting effect of CHOP on the apoptosis of LECs, and also to some extent improve the aggravation of pathological changes in cataract rats induced by overexpression of CHOP." (PMID 38771421, 2025).
colon adenocarcinoma (1 paper, 2024). "Western blot analysis demonstrated that murine colon adenocarcinoma cell line MC38 released EVs that also carry NUPR1." (PMID 38405101, 2024).
H1N1 virus infection (1 paper, 2022). "In the meantime, some downregulated genes (Muc2, Cyp2c55, and Nupr1) and upregulated gene (Slfn4) in response to H1N1 virus infection in mice were verified by Q-RTPCR." (PMID 35677448, 2022).
iron deficiency (1 paper, 2025). "Specifically, stem cell senescence is observed to promote tumor initiation through the Nupr1–lipocalin-2 pathway via the induction of functional iron deficiency." (PMID 40977764, 2025).
leprosy (1 paper, 2019). Leprosy is a chronic infectious disease affecting primarily the skin and peripheral nervous system. "We confirmed NUPR1 expression in leprosy lesions by qPCR of additional five T-lep and five L-lep samples and detected a 5.5-fold greater expression in L-lep vs. T-lep specimens." (PMID 31344041, 2019). "Together, these data indicate that M. leprae induces a cell fate program which includes NUPR1 as part of the host response in the progressive form of leprosy." (PMID 31344041, 2019). "Next, NUPR1 protein expression in leprosy skin lesions was evaluated by immunoperoxidase staining and concordantly, NUPR1 was more abundant in L-lep versus T-lep lesions." (PMID 31344041, 2019). "Finally, the overexpression of NUPR1 in lesions from the progressive forms of leprosy was validated by RT-qPCR and immunohistochemistry in skin biopsy samples, consistent with the finding that IFN-β induced genes are significantly enriched in L-lep lesions." (PMID 31344041, 2019). "Furthermore, NUPR1 mRNA and protein were upregulated in the skin lesions from patients with the multibacillary form of leprosy." (PMID 31344041, 2019). "Moreover, we also observed that NUPR1 was upregulated in the skin lesions from patients with the multibacillary form of leprosy." (PMID 31344041, 2019).
memory impairment (1 paper, 2020). "Here, we investigated the roles of miR-325-3p and Nupr1 in sevoflurane-induced learning and memory impairments in neonatal rats and HCN-2 human cortical neuronal cells." (PMID 32191629, 2020).
metabolic disorder (1 paper, 2020). "We conclude that long-term activation of mTORC1 by LTsc1KO, upstream regulators (Dddit4) of mTORC1 was impaired; meanwhile, expression of downstream genes (Nupr1 and FGF21) of mTORC1 was decreased, resulting in metabolic disorder and mitochondrial defects." (PMID 32363190, 2020).
non-alcoholic fatty liver disease (1 paper, 2022). "We found a strong association between NUPR1 and non-alcoholic fatty liver disease (hsa04932) as well as cholesterol metabolism (hsa04979)." (PMID 36307402, 2022). "Besides, functional enrichment analysis showed NUPR1 was associated with non-alcoholic fatty liver disease, a major risk factor for HCC." (PMID 36307402, 2022). "However, the functional significance of NUPR1 in non-alcoholic fatty liver disease was not addressed." (PMID 36307402, 2022).
prostate tumors (1 paper, 2022). "Overexpression of NUPR1 reduced the growth of prostate tumors in athymic mice model." (PMID 36499073, 2022).
pulmonary hypertension (1 paper, 2024). Increased pressure within the pulmonary circulation due to lung or heart disorder. "Nupr1 mediates PASMCs phenotypic transformation via STIM1signal axis, which results in the development of methamphetamine-related pulmonary arterial hypertension." (PMID 38347241, 2024). "Nupr1 plays a key role in the development of methamphetamine-related pulmonary arterial hypertension." (PMID 38347241, 2024).
rectal cancer (1 paper, 2025). A primary or metastatic malignant neoplasm that affects the rectum. "In addition, we analysed the relationship between NUPR1 expression and patient prognosis from 142 rectal cancer patients who received neoadjuvant therapy in the GEO (GSE87211) database." (PMID 40176685, 2025). "Additionally, we investigated its expression in rectal cancer patients receiving neoadjuvant chemoradiation in the TCGA data set and found a trend of higher expression of NUPR1 in nonresponse tumour." (PMID 40176685, 2025).
skin cutaneous melanoma (1 paper, 2025). "Subsequent analysis of scRNA‐seq data from patients with skin cutaneous melanoma (SKCM) treated with a combination of PD‐1 and cytotoxic T‐lymphocyte‐associated protein 4 (CTLA‐4) mAbs revealed exclusive expression of NUPR1 in macrophages." (PMID 40305758, 2025).
steatosis (1 paper, 2022). Increased lipid within the cytoplasm of cells. "Another potential beneficial effect of 2′-FL that may have contributed to the observed decrease in steatosis is the counter regulation of several important factors associated with ER stress such as ATF4, ATF6, ERN1, NUPR1 indicating an overall attenuation of the ER stress response." (PMID 35782914, 2022).
cancer (88 papers, 2012 to 2026). A tumor composed of atypical neoplastic, often pleomorphic cells that invade other tissues. "NUPR1 is implicated in numerous cancer-related processes, including cell cycle regulation, apoptosis, cell migration, invasion, adhesion, metastasis, and DNA repair responses." (PMID 41249113, 2025). "Increased expression of NUPR1 has previously been associated with poor patient outcomes in certain types of cancers." (PMID 38536720, 2024). "NUPR1 had been linked to the onset and progression of cancer, and it was commonly observed to be upregulated in different cancer forms." (PMID 39691708, 2024). "Because epigenetic alterations affect gene expression and are usually associated with cancer progression, we first examined the DNA methylation status of the NUPR1 promoter region." (PMID 38536720, 2024). "Overexpression of NUPR1 in non-cancer cells upregulated genes associated with extracellular vesicle biogenesis and incorporation." (PMID 38405101, 2024). "COPB2 interacted with NUPR1, which was a transcription factor associated with cancer development and advancement; NUPR1 produced a marked effect in cellular stress response and participated in tumor metastasis." (PMID 35600351, 2022). "Nuclear protein 1 (NUPR1) is a transcriptional coregulator that has been implicated in the development of various cancer types." (PMID 36307402, 2022). "NUPR1 is widely reported to be upregulated in multiple cancers and involved in many cancer-associated processes, including tumor growth, invasiveness, apoptosis, and autophagy." (PMID 36258210, 2022). "While NUPR1 has been reported in the initiation and progression of tumors, little is known on the mechanism(s) underlying the regulation of lipid metabolism of cancer cells by NUPR1." (PMID 36307402, 2022). "Treatments of cancer cells with siRNA directed against NUPR1 or with ZZW-115 induce a collapse of ATP, associated with a strong reduction in OXPHOS metabolism and overproduction of ROS." (PMID 34599149, 2021). "At the cellular level, NUPR1 has been described as participating in many processes associated with cancer, including cell cycle regulation and apoptosis, senescence, cell migration and invasion, development of metastases." (PMID 34599149, 2021). "Establishing the interactome of the cancer-associated stress protein Nuclear Protein 1 (NUPR1), we found that it binds to several hundreds of proteins, including proteins involved in nuclear translocation, DNA repair, and key factors of the SUMO pathway." (PMID 32780723, 2020). "At the cellular level, NUPR1 was involved in cancer-associated processes including cell-cycle regulation, apoptosis, senescence, cell migration and invasion, and metastases." (PMID 31667555, 2020). "During angiogenesis in cancer cells, NUPR1 was reported to be upregulated in association with triiodothyronine thyroid hormone receptor, which is regulated with TRH - Thyrotropin releasing hormone." (PMID 33008348, 2020). "At cellular level, NUPR1 was described to participate in many cancer-associated processes including cell-cycle regulation, apoptosis, senescence, cell migration and invasion, and development of metastases." (PMID 31744261, 2019). "Next, as NUPR1 has been reported to be associated with drug resistance in cancer cells, staurosporine-induced apoptosis was evaluated." (PMID 31138954, 2019). "The current study significantly contributes to a better understanding of mechanisms underlying the regulation of cell death by the cancer-associated protein, NUPR1." (PMID 30451898, 2018). "In the presented study, we show that Nupr1 expression is induced by Cr(VI) exposure, leading to the loss H4K16ac, a ‘hallmark’ of cancer." (PMID 27285315, 2016). "NUPR1 has been implicated in cancer-associated processes, although it remains poorly understood at the mechanistic level." (PMID 25056123, 2014).
cancer (continued). "Since NUPR1 functions in the regulation of cancer-associated gene expression networks, it is important to gain insight into the mechanisms by which these proteins are either activated or inactivated." (PMID 25056123, 2014). "Substantial evidence supports a maintenance role of the stress-inducible protein NUPR1 on cancer cell metabolism that confers chemotherapeutic resistance by upregulating mitochondrial function-associated genes and various antioxidant genes in cancer cells." (PMID 34359572, 2021). "Nuclear protein 1 (NUPR1) (also known as p8) is a molecule that has recently caught much attention owing to its association with chemotherapy resistance in a wide range of cancer types." (PMID 31138954, 2019). "Overexpression of Nupr1 has been implicated in a number of cancers." (PMID 27285315, 2016). "Thus, in spite of the association of Nupr1 to many pathobiological phenomena, details regarding the molecular mechanisms that contribute to the cancer-associated function of Kras have become an area of intensive investigation." (PMID 26617245, 2015). "Inactivation of NUPR1 thus changes multiple intracellular signals and affects cell function; it causes mitochondrial dysfunction, iron metabolic disorder, high ROS production and antioxidant defense impairment, all of which ultimately triggers ferroptosis in cancer cells." (PMID 34359572, 2021). "Together, these insights establish NUPR1 as a druggable stress-response node and provide a mechanistic framework to overcome resistance and refine adaptive cancer therapy paradigms." (PMID 42104400, 2026). "Mechanistically, statins impair the IR-mediated signaling and downregulate the stress-inducible transcription factor NUPR1, a known regulator of cancer progression." (PMID 41677647, 2026). "Previous studies have shown that NUPR1 can transcriptionally regulate genes involved in apoptosis and stress responses, including survivin, thereby promoting cancer cell survival." (PMID 41249113, 2025). "NUPR1 expression was examined across various cancer types, revealing the NUPR1+ macrophages were more abundant in tumors than in normal tissues." (PMID 40305758, 2025). "The NUPR1-dependent transcriptional program has been reported to either promote tumor or suppress it depending on the cancer context." (PMID 40707944, 2025). "In summary, this study provides valuable insights into enhancing the anticancer activity of NUPR1 inhibitors through combination with sorafenib, offering a promising new avenue for cancer therapy and opening new indications." (PMID 41249113, 2025). "This indicates that NUPR1 plays a protective role in helping cancer cells to increase resistance against stress and promoting survival against chemotherapy." (PMID 41249113, 2025). "This suggests that targeting NUPR1 can sensitize cancer cells to oxidative damage induced by sorafenib, broadening its therapeutic potential." (PMID 41249113, 2025). "NUPR1 can protect cancer cells from excess iron by inducing the expression of the iron-sequestering protein lipocalin-2 (LCN2)." (PMID 41429768, 2025). "Roles of NUPR1 in regulating proliferation, migration, and invasion of cancer cells have been reported in various types of cancer." (PMID 39085744, 2025). "NUPR1 has been identified as a key suppressor of ferroptosis in cancer cells, contributing to tumor progression in liver and pancreatic cancers." (PMID 40782567, 2025). "Treating cancer cells with NUPR1 inhibitors leads to cell death through various processes, including apoptosis, necroptosis, and ferroptosis." (PMID 41249113, 2025). "Kaplan–Meier survival analysis indicated that cancer patients with elevated NUPR1 expression in macrophages experienced significantly shorter OS, underscoring the potential of NUPR1+ macrophages as a biomarker for predicting resistance to cancer immunotherapy." (PMID 40305758, 2025).